TNF (tumor necrosis factor)
Diseases named in the same sentence as TNF in open-access papers (continued):
Sharing a sentence is not in itself a finding about the gene and the disease.
diabetic retinopathy (137 papers, 2007 to 2026). "VEGF regulation can partially inhibit the pathogenic effects of TNF-α, suggesting that the TNF-α signaling pathway is a critical therapeutic target for diabetic retinopathy." (PMID 40717698, 2025). "Future studies will also have to identify how other cytokines such as TNFα that have been associated with the development of diabetic retinopathy influence the regulation of the caspase-1/IL-β/IL-1R1 feedback signaling." (PMID 39483336, 2024). "The knockout of NRF2 in a mouse model of diabetic retinopathy increases TNF-α expression, causes earlier blood–retinal barrier breakdown, and exacerbates functional defects." (PMID 37627644, 2023). "Although TNF-α is also associated with the pathogenesis of diabetic retinopathy, TNF-α antagonist, etanercept, adalimumab, and infliximab fail to improve refractory DME." (PMID 35010703, 2021). "Concurrent with the increased expression of specific UPR markers, levels of MCP-1, and tumor necrosis factor α (TNF-α), cytokines associated with diabetic retinopathy were elevated." (PMID 28127564, 2017). "In previous studies using a TNF-α inhibitor, it has been demonstrated that TNF-α contributes to microvascular cell loss in diabetic retinopathy." (PMID 29240821, 2017). "Other cytokines such as interleukins and tumor necrosis factor α (TNF-α) are strongly associated with inflammatory disorders in the eyes, including diseases such as diabetic retinopathy with diabetic macular edema." (PMID 25679504, 2015). "TNFα has been identified as playing an important role in pathologic complications associated with diabetic retinopathy and retinal inflammation, such as retinal leukostasis." (PMID 25617622, 2015). "Since IGFBP-3 is protective to the diabetic retina and TNFα is causative in the development of diabetic retinopathy, we wanted to better understand the cellular mechanisms by which TNFα can reduce IGFBP-3 levels." (PMID 25073020, 2014). "Inflammatory mediators such as the tumor necrosis factor-alpha (TNFα) have been identified as an underlying factor causing the late blood-retinal barrier breakdown in diabetic retinopathy." (PMID 24300231, 2012). "Suppression of TNF-α by omega-3-polyunsaturated fatty acids reduces angiogenesis in a mouse model of oxygen-induced retinopathy as well as implicated in diabetic retinopathy." (PMID 22132311, 2011). "The susceptibility to diabetic retinopathy has been associated with TNF-α gene polymorphism and expression of human leucocyte antigen (HLA)-DR3 and HLA-DR4 phenotypes and HLA-DR4 phenotypes." (PMID 19641635, 2009). "Diabetic retinopathy is the primary manifestation of diabetic ophthalmic complications, and its occurrence is closely associated with the involvement of the inflammatory factor TNF-α." (PMID 40717698, 2025). "DNA hypomethylation of NLR family pyrin domain containing 3 (NLRP3) is associated with increased risk of diabetic retinopathy, and that of TNFα, TGFβ1 and MCP-1 is considered responsible for its increased expression in the serum of patients with proliferative diabetic retinopathy." (PMID 36672234, 2023). "Similarly, tumor necrosis factor-alpha was suggested as an independent risk factor for diabetic retinopathy." (PMID 37762893, 2023). "The results of the current study also suggest that MGCs can play an important role in regulating the expression of pro-inflammatory cytokines such as IL-1β, ΙL-6, TNF-α, and IL-18 in the early stages of diabetic retinopathy, which was proposed to be associated with the inflammasome activation." (PMID 34071438, 2021). "In fact, high-throughput sequencing indicated that the coexpressed gene, A2M (A2MD|CPAMD5|FWP007|S863-7) which encodes the α-2-macroglobulin that acts as a carrier of proinflammatory cytokines such as interleukin-1β, interleukin-6, and tumor necrosis factor-α, causes diabetic retinopathy." (PMID 32148491, 2020).
diabetic retinopathy (continued). "Inflammatory cytokines, such TNF, IL-6, and C-reactive protein, mainly produced by adipose tissue and macrophages, have been detected in the serum of type 2 diabetic patients and were associated with the microvascular complications of diabetic retinopathy." (PMID 30057551, 2018). "At the same time, the correlation of MALAT1 with both production of tumor necrosis factor-alpha (TNFα) in the septic cardiomyocytes model and inflammation in diabetic retinopathy has been scrutinized." (PMID 39798064, 2025). "This study aimed to evaluate the impact of anti-TNF (biological) therapies on the incidence and progression of diabetic retinopathy." (PMID 38842591, 2024). "Increased levels of proinflammatory cytokines such as tumor necrosis factor-alpha (TNF-α), interleukin-1 beta (IL-1β), and interleukin-6 (IL-6) have been detected in the vitreous and retina of people with diabetic retinopathy." (PMID 38918766, 2024). "Another study reported upregulation of CD40, TRAF2, and TRAF6 in patients with diabetic retinopathy, where CD40 was associated with the expression of pro-inflammatory molecules such as intercellular adhesion molecule 1 (CD54), CCL2, and TNFα." (PMID 38554187, 2024). "In summary, soluble secreted proteins of tears such as inhibition of ICAM-1 and TNF-α exert valuable effects on the prevention of early diabetic retinopathy." (PMID 39279894, 2024). "For example, tumour necrosis factor‐alpha (TNF‐α) is an inflammatory cytokine, and recent findings showed that elevated levels of this cytokine can predict the presence of diabetic retinopathy." (PMID 38718275, 2024). "Experimental models have documented the presence of a systemic pro-inflammatory environment with upregulation of CRP, IL-1β, IL-6 and TNFα before the appearance of any pathological characteristic of diabetic retinopathy." (PMID 36672234, 2023). "A comparative analysis between humans and rodents indicates that proinflammatory factors such as TNF-α, IL-1β and IL-6 are correlated with diabetic retinopathy." (PMID 37670018, 2023). "Both in vitro and in vivo models of diabetic retinopathy have been used to evaluate a role for Cx43 mediated communication when treated with IL1ß and TNFα in the presence of high glucose." (PMID 35054783, 2022). "For example, patients with diabetic retinopathy show increased levels of IL1β and TNFα in vitreous humor and serum." (PMID 35883547, 2022). "Elevated levels of pro-inflammatory cytokines such as IL-1β, TNF-α and IL-6 were found in the retinae of patients with diabetic retinopathy, as well as in mouse or rat models of diabetic retinopathy." (PMID 35309305, 2022). "Activated microglia and Müller cells release proinflammatory cytokines including IL-1β and TNF-α in diabetic retinopathy." (PMID 35010703, 2021). "A few studies have reported that BQ123 suppresses the ET1-ETAR system-mediated inflammatory cytokine TNFα, preventing inflammation-induced airway smooth muscle hyperplasia and diabetic retinopathy." (PMID 33828553, 2021). "Here, we found MP activation in human diabetic retinopathy, especially in neovessels from human neovascular membranes in proliferative retinopathy, including TNF-α expression." (PMID 34673570, 2021). "Alterations in the microbiome were associated with increases in gut mucin, goblet cell number, villi length, and tauroursodeoxycholate bile acid and reductions in plasma peptidoglycan, retinal TNF-α mRNA and diabetic retinopathy." (PMID 34906176, 2021). "TNF-α increases bovine retinal endothelial cell (BREC) permeability through the protein kinase C (PKC) pathway in diabetic retinopathy." (PMID 31263416, 2019). "In diabetic retinopathy, there is an increase of pro-inflammatory cytokines and chemokines like monocyte chemoattractant protein 1, TNFα, interleukin 1β (IL-1β) and IL-6." (PMID 31739614, 2019). "It was demonstrated that TNF has an important role in the pathogenesis of diabetic retinopathy, being an important inducer of endothelial cell apoptosis." (PMID 30057551, 2018).
diabetic retinopathy (continued). "Genistein, a bioactive flavonoid, attenuates diabetic retinopathy by inhibiting tyrosine kinase, proinflammatory cytokine production, TNF-α activation, and microglial activation." (PMID 29937497, 2018). "It is well established that early diabetic retinopathy following streptozotocin (STZ) injections leads to increased TNF-α levels." (PMID 29095817, 2017). "It has also been found that the protective effect of RvD1 against diabetic retinopathy occurs in part through the suppression of TNF-α." (PMID 29095817, 2017). "Several identified genes with altered DNA methylation in cases with PDR, such as TNF, CHI3L1, and CHN2, encode proteins with previous known function in diabetic complications and/or diabetic retinopathy." (PMID 26248552, 2015). "It was found that inflammatory mediators such as TNF-α and IL-1β contribute to the pathogenesis of diabetic retinopathy and significantly higher levels of these markers were found in diabetic vs. healthy control subjects." (PMID 26262605, 2015). "In animals, proinflammatory cytokine levels are increased in the retina of diabetic animals, and inhibition of TNF-α exerts beneficial effects in the prevention of early diabetic retinopathy." (PMID 26137497, 2015). "Proinflammatory cytokines, as TNF and IL-1β, were found to be increased in the vitreous of patients with diabetic retinopathy, as well as IL-6." (PMID 25873768, 2015). "TNF-α has been reported to be upregulated in diabetic retinopathy and promotes retinal leukostasis, blood-retinal barrier breakdown and capillary degeneration." (PMID 26710229, 2015). "Our findings establish IGFBP-3 as a pivotal regulator of the insulin receptor/TNFα pathway and a potential therapeutic target for diabetic retinopathy." (PMID 24695399, 2014). "For these studies, primary human retinal endothelial cells (REC) were used since these cells undergo TNFα-mediated apoptosis under conditions of high glucose conditions and contribute to diabetic retinopathy." (PMID 25073020, 2014). "The inflammatory profile of diabetic retinopathy has been confirmed in animal models of diabetes, where an increase was found in the levels of IL-1β and TNF in the retina." (PMID 25132733, 2014). "In early diabetic retinopathy, there is an increased release of retinal inflammatory mediators including TNF-α 85, IL-1β, ICAM-1, and angiotensin II along with activation of microglial cells." (PMID 23365490, 2013). "Strong correlations between enhanced inflammatory biomarkers, including TNF-alpha, and the occurrence of diabetic retinopathy have been reported through extensive studies by many researchers." (PMID 24259948, 2013). "A soluble TNF-α receptor-Fc hybrid, such as etanercept, is able to normalize vascular permeability and leukostasis; this suggests that TNF-α contributes to diabetic retinopathy, perhaps by preventing endothelial-cell damage from adhering leukocytes." (PMID 23365490, 2013). "Many studies demonstrated that VEGF and TNF-α contribute to the progression of diabetic retinopathy and that their expression is increased in the diabetic retina." (PMID 23762874, 2013). "The role of the inflammatory cytokine TNF-α in the pathogenesis of diabetic retinopathy is well established." (PMID 23587252, 2013). "In diabetic rats, curcumin significantly reduced TNF-α levels in the retina, prevented experimental diabetic retinopathy, decreased MCP-1 and ICAM-1 levels in the kidney, and ameliorated macrophage infiltration." (PMID 23285282, 2012). "Microglial-mediated release of TNF-α and IL-1β is a mechanism by which a pro-inflammatory environment exists in the diabetic retina and contributes to the development of experimental diabetic retinopathy." (PMID 22132311, 2011). "Increased production of IFN-γ or TNF-α has been observed in uveoretinitis, diabetic retinopathy, and age-related macular degeneration." (PMID 21738388, 2011).
diabetic retinopathy (continued). "There is strong evidence that tumor necrosis factor-α (TNFα) is involved in inflammatory processes in diabetic retinopathy." (PMID 20856927, 2010). "After having shown that genistein exhibits profound reduction in both TNF-α expression and release, we next sought to explore a potential mechanism by which genistein regulates inflammation in diabetic retinopathy." (PMID 21042558, 2010). "This leads us to the conclusion that TNF-α is a major player in retinal cell death in diabetic retinopathy." (PMID 19641635, 2009). "Increased levels of IL-1ß and TNF-α have been detected in the serum and vitreous of patients with diabetic retinopathy, and these cytokines have been shown to induce inflammatory responses in HRECs." (PMID 20011631, 2009). "Our data identify TNF-α as a key molecule in the pathogenesis of the early signature pathologies and later diabetic complications that characterize diabetic retinopathy." (PMID 19641635, 2009). "We have previously demonstrated that TNF-α increases early during the course of diabetic retinopathy." (PMID 19641635, 2009). "Our data emphasize the role of TNF-α in signature pathologies in both early and late diabetic retinopathy." (PMID 19641635, 2009). "Additionally, in models of diabetic retinopathy, UA reduced inflammation (IL-6, IL-1β, TNF-α) and oxidative stress by increasing levels of SOD and GSH while decreasing MDA, effects associated with activation of the Nrf2/HO-1 pathway." (PMID 41374004, 2025). "The pathogenesis of diabetic retinopathy is related to inflammation and fibrosis, and it has been reported that the production of pro-inflammatory cytokines such as IL-1, TNF-α, and VEGF increases in the vitreous body of patients with diabetic retinopathy and in animal models of the retina." (PMID 38650715, 2024). "Microglia and astrocytes are also two main sources of ROS seen in chronic degenerative neuronal diseases, and in experimental models of diabetic retinopathy, increased production of AGEs and ROS are shown to activate retinal microglia, increasing the production of cytokines, TNF-α and IL-β." (PMID 36672234, 2023). "In addition, melatonin was shown to prevent the production of pro-inflammatory cytokines such as IL-1β and TNF-α in diabetic retinopathy." (PMID 35455066, 2022). "Accordingly, the topical administration of d-MAPPSTM could result in the inhibition of TNF-α- and IL-1β-driven inflammation in retinal tissue and may be crucial in the prevention of diabetic retinopathy." (PMID 36362313, 2022). "This condition induces the secretion of tumor necrosis factor-α (TNF-α) and the localized secretion of other proinflammatory cytokines, growth factors and bioactive molecules that play important roles in the onset and progression of diabetic retinopathy." (PMID 35409409, 2022). "In addition, and building on their in vitro observations, the team developed an in vivo model of diabetic retinopathy in which pro-inflammatory cytokines, IL1β and TNFα, were injected into the vitreous of NOD mice." (PMID 35054783, 2022). "Likewise, IL-17A, IL-6, and TNF-α are the primary cytokines involved in retinal inflammation, retinal vascular impairment, and the progression of diabetic retinopathy." (PMID 33919327, 2021). "Many of those mediators have become research spots as they may stand as potential therapeutic targets for the treatment of diabetic retinopathy, IL-1β and TNF-α should be counted." (PMID 32019593, 2020). "Additionally, it is known that there is an increase in pro-inflammatory cytokines like TNFα in diabetic retinopathy." (PMID 31739614, 2019). "Furthermore, patients with fibromyalgia and severe diabetic retinopathy have reduced mitochondrial DNA and elevated TNFα in their peripheral blood compared to control groups." (PMID 31814879, 2019). "Furthermore, TNF-α is up-regulated in the eyes of patients with diabetic retinopathy and elicits reactive oxygen species (ROS) production and oxidative stress in human RPE cells." (PMID 30013474, 2018).
diabetic retinopathy (continued). "However, an apparent contradiction arose regarding if the presence of TNF is more important for BRB breakdown in the initial or late phases of diabetic retinopathy." (PMID 30057551, 2018). "Epigenetic modifications of TNF in T1D subjects may subsequently regulate the expression of TNF and thereby contribute to inflammation in diabetic retinopathy." (PMID 26248552, 2015). "CD40 and TNF-α are also central to the development of diabetic retinopathy while CX3CL1 may play a role in the pathogenesis of this retinopathy." (PMID 26710229, 2015). "Among numerous effects promoted by TNF in the CNS, particularly in the retina, several are intimately related to alterations observed in diabetic retinopathy, such as increased endothelial cell permeability, breakdown of BRB, and induction of leukocyte adhesion." (PMID 25873768, 2015). "Our previous studies in retinas of diabetic rats have shown that Compound 49b, a novel β-adrenergic receptor agonist, prevented diabetic changes by increasing IGFBP-3 and decreasing TNFα, thus restoring insulin signaling and protection against diabetic retinopathy." (PMID 24695399, 2014). "TNFα is a key player in diabetic retinopathy, as well as other ocular pathologies." (PMID 25073020, 2014). "Our hypothesis was that inhibition of TNFα actions in β2KO mice would restore normal insulin signal transduction, explaining the improvement in markers of diabetic retinopathy reported by others." (PMID 25138272, 2014). "Interestingly, anti-inflammatory drugs prevent early events in diabetic retinopathy via TNF-α suppression, and TNF-α inhibition in vivo reduces the loss of microvascular cells." (PMID 20300563, 2010). "The involvement of TNF-α in the pathogenesis of diabetic retinopathy could be attributed, in part, to its proinflammatory activity." (PMID 19641635, 2009). "Together with our previous data demonstrating the role of TNF-α on diabetic vascular leakage, we can conclude from this study that TNF-α is one of the major cytokines in diabetic retinopathy both involved in leukocyte activation as well as in endothelial cell apoptosis." (PMID 19641635, 2009). "TNF-alpha is a cytokine involved in the pathogenesis of diabetic retinopathy and, therefore, it could also be possible that the lower levels of CST detected in diabetic patients were the consequence rather than the cause of inflammation." (PMID 18709137, 2008). "The early introduction of the TNF-α antagonists to the treatment of young patients with DM type 1 who show high serum activity of the cytokine may prevent developmentof diabetic retinopathy." (PMID 17641733, 2007). "The early introduction of the TNF-α antagonists to the treatment of young patients with DM type 1 who show high serum activity of the TNF-α may prevent them from development of diabetic retinopathy." (PMID 17641733, 2007). "Moreover, increased levels of TNF-α are detected in diabetic patients and may serve as a prognostic tool for diabetic retinopathy." (PMID 31992349, 2020). "Additionally, TNF could be a good therapeutic target for the prevention of diabetic retinopathy progression." (PMID 30057551, 2018). "Therefore, it is clear that inhibition of TNFα is protective against diabetic retinopathy changes; however, the mechanism by which this may occur is unknown." (PMID 25138272, 2014). "Therefore, the role of inflammation is unequivocal in diabetic retinopathy, from the leukocyte adhesion to the increase in inflammatory mediators, such as TNF, which exerts a crucial role in blood retinal barrier breakdown, as well as the death of retinal neurons." (PMID 25132733, 2014). "Furthermore, the BRB breakdown in diabetic retinopathy has been shown to require TNF-α." (PMID 22993483, 2012). "Thus, studies presented here indicate AGEs and TNF-α could contribute to diabetic retinopathy through FOXO1-mediated pericyte apoptosis." (PMID 20300563, 2010).